EDN1 (endothelin 1)
Diseases named in the same sentence as EDN1 in open-access papers (continued):
Sharing a sentence is not in itself a finding about the gene and the disease.
heart failure (continued). "In contrast, we did find increased levels of endothelin-1 in the more severe forms of chronic Chagas disease, which was consistent with the findings in uninfected subjects suffering from heart failure, who are known to present with neurohormonal activation and a high degree of endothelial injury." (PMID 31199841, 2019). "Endothelin-1 participates in the pathophysiology of heart failure." (PMID 24523936, 2014). "Compensatory elevation of endothelin-1 activity can be measured in heart failure and AF." (PMID 25401728, 2014). "One study showed that endothelial cell-derived endothelin-1 promotes cardiac fibrosis and heart failure in diabetic hearts through stimulation of EndoMT as these effects did not occur in hearts from transgenic mice with endothelial cell specific endothelin-1 deletion." (PMID 24175099, 2013). "Endothelin 1 mRNA expression levels in lungs from ascitic chickens were 2.5 to 2.9-fold higher than levels from healthy birds (P < 0.05) both in control and cold-treated groups of broilers, whereas levels in animals with cardiac failure were intermediate." (PMID 24286074, 2013). "BNP is used for the diagnosis of heart failure and cardiac dysfunction and its synthesis in cardiomyocytes is induced by cellular stress such as mechanical stretch, hypoxia, and metabolic stress, as well as various paracrine signals such as endothelin-1 and cytokines." (PMID 32185414, 2020). "As far as we know, this study, for the first time, showed that endothelin-1 gave the edge to the Japan Score over the STS Score in heart failure, and BNP, determining endothelin-1, was deemed to have an adverse cardiac effect." (PMID 40385809, 2025). "The objective is to investigate the relationship between sepsis complicated with heart failure and the expression levels of CXC chemokine ligand 8 (CXCL8) and endothelin-1 (ET-1)." (PMID 36065195, 2022). "Moreover, furin and its substrates, including tumornecrosis factor-α (TNF-α), endothelin-1 (ET-1), and transforminggrowth factor-β1 (TGF-β1), are capable of mediating inflammation,hypertrophy, and fibrosis in MI and heart failure." (PMID 38481703, 2024). "We found higher endothelin 1 mRNA levels in ascitic broilers, both in control and cold treated groups, than corresponding levels for healthy broilers and broilers with cardiac failure but without ascites (P < 0.05)." (PMID 24286074, 2013). "Furthermore, endothelin-1 has been demonstrated to activate NOX for the generation of oxidative stress via the involvement of the ETA-proline-rich tyrosine kinase-2 and Rac 1 pathway and, thus, can be seen to induce heart failure." (PMID 38786079, 2024). "However, observations that over expression of the EDN1 gene leads to a lethal heart failure that is not prevented by ERA indicate that there are undiscovered aspects of endothelin biology that require further investigation." (PMID 28694457, 2017). "It was demonstrated that adrenomedullin (ADM) and endothelin-1 (ET-1) contribute to the alterations in systemic vascular resistance and that ADM may act to improve left ventricular function during static exercise, especially in patients with heart failure and healthy older men." (PMID 23487485, 2012).
ischemia (102 papers, 2008 to 2025). A hypoperfusion of the BLOOD through an organ or tissue caused by a PATHOLOGIC CONSTRICTION or obstruction of its BLOOD VESSELS, or an absence of BLOOD CIRCULATION. "Applying the peptide endothelin-1 (ET-1) to blood vessels also causes strong and long-lasting vasoconstriction and hypoxia, which can block blood flow and lead to downstream ischemia." (PMID 37409019, 2023). "Hyperglycemia can induce an increase in the synthesis of endothelin-1 by kidney cells, which can further aggravate renal tissue ischemia and increase the risk of AKI in patients with PNS." (PMID 35247980, 2022). "We induced focal ischemia in a mouse brain by injecting the vasoconstrictor endothelin-1, which induces transient ischemia, followed by delayed neuronal loss." (PMID 35216419, 2022). "It is known that endothelin-1 (ET-1) is a peptide hormone, encoded by Edn1 gene, with potent vasoconstrictor properties and is commonly involved in ischemia/hypoxia-associated microvascular endothelium." (PMID 31660990, 2019). "Endothelin-1 (ET-1) microinfused above middle cerebral artery caused a rapid reduction of rCBF (ischemia) which lasted for 30 minutes and was followed by a gradual recovery of blood flow (reperfusion) within the striatal region." (PMID 26146654, 2015). "The level of endothelin-1 (ET-1), a potent vasoconstrictor, was associated with retinopathy under ischemia." (PMID 22053184, 2011). "Additionally, smoking induces the release of endothelin-1 into blood vessels, causing vasoconstriction and subsequent ischemia in organs and leading to structural changes and dysfunction." (PMID 40415015, 2025). "Once activated, endothelial cells secrete endothelin-1 (ET-1), von Willebrand factor (vWF), nitric oxide, and endothelial nitric oxide synthase, resulting in unstable vascular tone, with decreased vasodilation and increased vasoconstriction causing ischemia and tissue hypoxia." (PMID 37886934, 2023). "The first model utilized endothelin–1 (ET–1), a vasoconstrictor peptide, to induce focal ischemia within the mPFC." (PMID 38137132, 2023). "Infusion of endothelin-1 (ET-1), as a potent vasoconstrictor, into the animal’s hippocampus using stereotaxic surgery is a method that is frequently used to develop an ischemia model." (PMID 35317197, 2022). "The data showed that an endothelin-1-induced ischemia model exhibited considerably damaged neurological function; in these models, mNSSs were lower than those in sham rats." (PMID 34638996, 2021). "A previous study confirmed microinjection of endothelin-1 [ET-1] as an effective method to induce acute focal ischemia where striatum and parietal cortex were damaged." (PMID 34205911, 2021). "We investigated endothelin-1, nitric oxide metabolites, asymmetric dimethylarginine during cardiopulmonary bypass: before ischemia, after ischemia, and after reperfusion." (PMID 32727110, 2020). "We employed the endothelin-1 (ET-1) model to induce focal ischemia in the right sensorimotor cortex of Sham and Ovx female rats and measured the spontaneous neurovascular recovery in the chronic stage." (PMID 30271324, 2018). "Following four short episodes of hind limb ischemia and reperfusion (remote ischemic preconditioning stimulus), there was an increase in the levels of endothelin 1 in the plasma in comparison to ischemia-reperfusion group." (PMID 30026513, 2018). "Endothelin-1 (ET-1), a vasoconstrictor, has recently been used to induce focal ischemia in rodents and marmoset monkeys." (PMID 28358140, 2017). "A focal reperfusion model of ischemia was induced in conscious SHR by administering endothelin-1 to the middle cerebral artery (MCA)." (PMID 24752645, 2014). "Hippocampal silent ischemia was induced by infusion of endothelin-1 (ET-1), a potent vasoconstrictor, into either the dorsal or the ventral hippocampus (dHPC and vHPC)." (PMID 25136299, 2014).
ischemia (continued). "The middle-aged rats subjected to endothelin-1-induced ischemia showed robust behavioral and EEG changes, which were more severe and longer lasting than in young rats." (PMID 24245542, 2013). "Stereotaxic application of endothelin-1 to the middle cerebral artery is now a well established method of focal ischemia in conscious rats with recent adaption of the model for use in primates." (PMID 23401848, 2013). "Similar changes in GFAP and laminin distribution were also found in areas of focal ischemia induced by endothelin-1 (ET-1), a vasoconstrictor peptide upregulated by pilocarpine before the appearance of vasogenic edema." (PMID 24015271, 2013). "Endothelin-1 (ET-1) is a potent vasoconstrictor that can be used to induce ischemia directly when applied topically or injected intracerebrally or indirectly if injected proximal to the MCA." (PMID 23343500, 2013). "The ischemia results from the intraspinal injection of the vasoconstrictive agent endothelin-1 (ET-1)." (PMID 22564441, 2012). "The present study was a proof of concept study to evaluate Wnt3a treatment using the endothelin-1 focal ischemia model." (PMID 22815838, 2012). "An imbalance between nitric oxide (NO) and endothelin-1 (ET-1) contributes to dysregulated vasomotor tone: decreased endothelial NO synthase (eNOS) activity impairs vasodilation, while increased ET-1 promotes sustained vasoconstriction and ischemia." (PMID 41010412, 2025). "In addition, chronic intermittent hypoxemia contributed to the disequilibrium of arginase-endothelial nitric oxide synthase and enhanced expression of endothelin-1, leading to vascular remodeling and ischemia." (PMID 39045383, 2024). "Imbalance between vasodilating and vasoconstricting agents with reduced production of nitric oxide (NO) and enhanced production of endothelin-1 (ET-1) may lead to ischemia / reperfusion and subsequent increased oxidative stress which impact on EC." (PMID 34487318, 2023). "More recent research has shown the conversion of astrocytes to iN cells in a focal ischemia model induced by the vasoconstrictive peptide endothelin-1, resulting in 30–40% regeneration of lost neurons in the motor cortex of adult mice and in the improvement of neurological dysfunctions." (PMID 34068607, 2021). "In this study, we employ temporal histopathology of cerebral vasculature in a rat model of β-amyloid (Aβ) toxicity and endothelin-1 induced-ischemia (ET1) to investigate the panorama of cerebral pathology and the protein expression on d1, d7, and d28 post-injury." (PMID 30971910, 2019). "Furthermore, treatment of DJ-1 knockout mice with ND-13, following Endothelin-1 induced ischemia, resulted in significant improvement in motor functions, suggesting that ND-13 provides compensation for DJ-1 deficits." (PMID 29489843, 2018). "This study aimed to determine whether the expression of endothelin-1 and its receptors are regulated in the myocardium and in coronary arteries after experimental ischemia-reperfusion." (PMID 28323857, 2017). "Depending on the concentration of endothelin-1, the severity and duration of ischemia as well as the resulting infarct size may be modified." (PMID 28064357, 2017). "In this study, we describe the patterns of microglia activation, astrocytosis, oligodendrocyte damage, Nogo-A immunoreactivity, and myelin impairment from 3 days to 30 days following focal ischemia induced by microinjections of endothelin-1 (ET-1) into the rat striatum." (PMID 28090244, 2016). "Vasoconstrictive agent endothelin-1 was injected into the rat spinal cord to induce ischemia." (PMID 22564441, 2012). "The release of endothelin-1 may promote vasoconstriction, whereas the production of von Willebrand factor (vWF) shifts the hemostatic balance towards a procoagulant state, resulting in coronary arteries’ thrombosis, and subsequent ischemia." (PMID 36837440, 2023). "Interestingly, similar results were observed in focal ischemia induced by endothelin-1." (PMID 33429982, 2021).
ischemia (continued). "Similarly, expression of CCL2 was induced in human brain-derived EC by endothelin-1 and ischemia." (PMID 20047691, 2010). "In the presence of ischemia, the expression of VEGF, stromal cell-derived factor 1 (SDF-1), hepatocyte growth factor (HGF), and endothelin 1 (ET-1) is increased, thereby stimulating the recruitment of EPCs to the ischemic sites." (PMID 37899988, 2023). "In a rat focal ischemia model induced by endothelin-1 injection, CDK5 activity increased at 3, 12, and 24 h after ischemia in both cells’ cytoplasm and nuclei." (PMID 33429982, 2021). "Compared to baseline, levels of Edn1 mRNA in WT and HDAC 2-/- kidneys were elevated several-fold at 24 h post-ischemia, though levels in WT mice were significantly higher than in HDAC2-/- mice (p = 0.046)." (PMID 33907245, 2021). "A high intra-compartmental pressure is responsible for the initiation of ischemia, hypoxia and necrosis of the muscle and this promotes the release of vasoactive substances, namely vascular endothelial factor (VEGF), endothelin-1 (ET-1) and nitric oxide (NO)." (PMID 25881255, 2015). "Endothelin-1 stimulates fibroblasts to convert to activated myofibroblasts with increased ECM secretion, intimal hyperplasia, luminal narrowing, reduced capillary blood flow vessel obliteration and ischemia." (PMID 37886934, 2023). "Activated cardiac myofibroblasts produce pro-inflammatory cytokines (interleukin-1 (IL-1), IL-6 and TGF-β), vasoactive proteins (Ang II, endothelin-1 (ET-1), atrial natriuretic peptide (ANP) and B-type natriuretic peptide (BNP)), noradrenaline, ischemia, reperfusion, and mechanical stimuli." (PMID 33809061, 2021). "However, when added ET‐1, this effect of NA‐1 was notably counteracted After NA‐1 administration, the synthesis of ONOO− and endothelin‐1 decreased, which inhibited pericyte‐mediated vasoconstriction following ischemia and recanalization." (PMID 40415486, 2025). "Elevated levels of endothelin-1, metalloproteinase and NO levels could subsequently have exerted cerebral vasodilatory effects and concomitantly induced cerebral cellular injury, probably not ischemia related." (PMID 33926378, 2021).
Insulin resistance (95 papers, 2008 to 2025). Increased resistance towards insulin, that is, diminished effectiveness of insulin in reducing blood glucose levels. "Insulin resistance can cause renal injury through renin-angiotensin system activation, increases in aldosterone and angiotensin II with subsequent effects on endothelin-1 and insulin-like growth factor-1, and the generation of reactive oxygen species." (PMID 35885048, 2022). "On the other hand, the hyperinsulinemia associated with vascular insulin resistance increases the release of endothelin-1 (ET-1) via a mitogen-activated protein kinase (MAPK)-dependent signaling pathway." (PMID 36012219, 2022). "Vascular dysfunction associated with insulin resistance is characterized by loss of nitric oxide (NO)-mediated vasodilation and heightened endothelin-1 induced vasoconstriction, as well as capillary rarefaction." (PMID 34966295, 2021). "Consequently, insulin resistance is associated with an imbalance between nitric oxide and endothelin-1 resulting in vasoconstriction and proliferation of vascular smooth muscle cells." (PMID 38025208, 2023). "Additionally, insulin resistance is associated with increased expression of endothelin-1, which worsens ED by mediating vasoconstriction." (PMID 31947853, 2020). "Several novel cardiac stress biomarkers like C-terminal pro-arginine-vasopressin (copeptin), C-terminal pro-endothelin-1 (CT-proET-1) and mid-regional pro-adrenomedullin (MR-proADM) were positively associated with metabolic syndrome and insulin resistance in cross-sectional settings." (PMID 33066780, 2020). "It is known that MAPK activation by IRS-1 causes the release of endothelin-1, which promotes insulin resistance (by reducing blood supply to the skeletal muscle), increases oxidative stress, reduces the bioavailability of NO, and promotes a proatherogenic state." (PMID 23573411, 2013). "In addition, ET-1 levels are associated with insulin resistance and impairment of glucose transport, and the one common polymorphism in the EDN1 gene (rs5390 - Lys198Asn) has been reported to be associated to blood pressure in interaction with body mass index in European and Japanese populations." (PMID 26040574, 2015). "Hyperinsulinemia and chronic inflammation, common in insulin resistance and type 2 diabetes, promote the overexpression and secretion of endothelin-1 (ET-1), a potent endothelium-derived vasoconstrictor." (PMID 41235339, 2025). "The effects of this increase in the levels of endothelin-1 in combination with elevated insulin resistance and decreased glucose uptake depend on the target tissue because the expression and activation of endothelin receptor subtypes are tissue-specific." (PMID 39518432, 2024). "Meanwhile, hyperinsulinemia and vascular insulin resistance also activate the mitogen-activated protein kinase (MAPK)-dependent signaling pathway to increase the release of endothelin-1 (ET-1) which further promotes vascular constriction." (PMID 38255878, 2024). "Animal studies have shown that a high-fat diet led to increased islet Edn1 levels in mice, whereas blocking endothelin-1 type B receptor improved glucose intolerance and insulin resistance in mice." (PMID 36675322, 2023). "Specifically, it was proposed that insulin resistance leads to an imbalance between NO and endothelin-1 (ET-1) production, with the effects of ET-1 (vasoconstriction) prevailing over NO-induced vasodilation." (PMID 32326182, 2020). "For example, in adipocytes GRK2-mediated endothelin-1-induced insulin resistance occurs by two mechanisms, one of which is a GRK2 kinase-independent inhibition of activation of Gαq/114." (PMID 31554835, 2019). "NO stimulates the insulin release and the equilibrium between NO and endothelin-1 with a predominium of endothelin-1 inducing insulin resistance." (PMID 31191339, 2019). "The increase in BP was accompanied by increased insulin levels, insulin resistance, and increased levels of endothelin-1." (PMID 29882756, 2018).